ACAD9 (acyl-CoA dehydrogenase family member 9)
Description:
Together with NDUFAF1 and ECSIT, forms part of the mitochondrial complex I (MCIA),which is required for the biogenesis of respiratory Complex I (CI) and is therefore crucial for the activation of the oxidative phosphorylation system. ECSIT binding triggers a large conformational change, switching ACAD9 from a fatty acid oxidation (FAO) enzyme to a CI assembly factor. The function in CI assembly is independent of the fatty acid oxidation (FAO) activity of the protein. As FAO enzyme, it catalyzes the first step in mitochondrial FAO, which consists in the proR-proR stereospecific alpha, beta-dehydrogenation of fatty acyl-CoA thioesters using the electron transfer flavoprotein (ETF) as their physiologic electron acceptor, resulting in the formation of trans-2-enoyl-CoA ((2E)-enoyl-CoA). Its preferred substrates are both saturated and unsaturated long-chain acyl-CoA substrates, with optimum activity toward the latter. In addition, based on its established catalytic mechanism, and combined genetic interaction or mutant phenotype evidence, it is predicted to act also on substrates that have not been tested experimentally but are metabolized by mitochondrial FAO, including long-chain unsaturated fatty acids such as linoleate (9Z,12Z-octadecadienoate), linolenate (9Z,12Z,15Z-octadecatrienoate), and others. Among the different mitochondrial acyl-CoA dehydrogenases, its FAO activity overlaps with that of ACADV and ACADL, but plays a primary role in tissues where it is the main long-chain ACAD expressed, such as the central nervous system. It differs significantly from ACADVL in the use of polyunsaturated substrates in vitro, especially docosahexaenoic acid (which is not primarily used for energy but mainly beta-oxidized in the peroxisomes).
Synonyms: NPD002; MGC14452; MC1DN20
Tractability: Small molecule: a structure with a bound ligand is known. Antibody: UniProt places it where antibodies can reach, with high confidence. PROTAC: ubiquitination databases record sites on it; its protein half-life has been measured.
Target class: Enzyme; Oxidoreductase
Gene: Protein-coding gene on chromosome 3 (128,879,596 to 128,924,003, forward strand). Ensembl gene ENSG00000177646.
Subcellular location: Mitochondrion inner membrane
Subcellular location (Human Protein Atlas): Mitochondria
Pathways (Reactome):
Metabolism: Complex I biogenesis
Gene Ontology:
Molecular function: acyl-CoA dehydrogenase activity; long-chain fatty acyl-CoA dehydrogenase activity; medium-chain fatty acyl-CoA dehydrogenase activity; protein binding; protein-macromolecule adaptor activity; very-long-chain fatty acyl-CoA dehydrogenase activity; flavin adenine dinucleotide binding; oxidoreductase activity, acting on the CH-CH group of donors
Biological process: long-chain fatty acid metabolic process; medium-chain fatty acid metabolic process; mitochondrial respiratory chain complex I assembly; fatty acid metabolic process
Cellular component: dendrite; mitochondrial complex I intermediate assembly complex; mitochondrial membrane; mitochondrion; nucleus; mitochondrial inner membrane
Genetic constraint (gnomAD): Loss-of-function variants: 52 observed, 74.14 expected, observed/expected ratio (o/e) 0.7, 90% interval 0.56 to 0.88. The upper end of that interval is the gene's LOEUF score, 0.88, which puts it in group 3 of 6, group 1 being the genes least tolerant of losing a copy. Missense variants: 769 observed, 837.21 expected, observed/expected ratio (o/e) 0.92, 90% interval 0.87 to 0.98. Synonymous variants: 312 observed, 328.18 expected, observed/expected ratio (o/e) 0.95, 90% interval 0.87 to 1.04.
Gene-disease validity (ClinGen):
ClinGen rates the evidence that ACAD9 causes each of these diseases.
acyl-CoA dehydrogenase 9 deficiency (autosomal recessive): Definitive. A rare disorder leading to a deficiency of complex I of the respiratory chain and is characterized by neurological dysfunction, hepatic failure and cardiomyopathy.
Homologues: Orthologues: chimpanzee ACAD9 (100% identical), macaque ACAD9 (97% identical), rabbit ACAD9 (88% identical), mouse Acad9 (86% identical), pig ACAD9 (86% identical), dog ACAD9 (86% identical), rat Acad9 (86% identical), tropical clawed frog acad9 (73% identical), zebrafish acad9 (68% identical), Caenorhabditis elegans acdh-1 (24% identical), Caenorhabditis elegans acdh-8 (22% identical), Caenorhabditis elegans acdh-10 (21% identical), and 5 more. Paralogues in human: ACADVL (45% identical), ACADS (24% identical), ACADSB (24% identical), IVD (23% identical), ACADM (22% identical), ACAD8 (21% identical), GCDH (19% identical), ACOX3 (19% identical), ACADL (18% identical), ACAD10 (17% identical), ACAD11 (17% identical), ACOXL (15% identical), and 2 more.
Diseases named in the same sentence as ACAD9 in open-access papers:
ACAD9 is named in the same sentence as 61 diseases in open-access papers, as found by Europe PMC text mining. Sharing a sentence is not in itself a finding about the gene and the disease. The quoted sentences say what the papers report.
cardiomyopathy (12 papers, 2012 to 2025). A disease of the heart muscle or myocardium proper. "For instance, riboflavin was used more often in cardiomyopathy, targeting potential deficiency of ACAD9, FAD synthase or multiple acyl‐CoA dehydrogenase." (PMID 39529390, 2025). "To date, ACAD9 deficiency, known as a recessive neuromuscular disease, is often characterized by early symptoms and even severe neonatal clinical signs such as cardiomyopathy and neurological and liver dysfunctions." (PMID 40806260, 2025). "Acyl-CoA dehydrogenase family member 9 (ACAD9) is an enzyme essential for the assembly of mitochondrial respiratory chain complex I. ACAD9 deficiency can cause lactic acidosis, myopathy, cardiomyopathy, intellectual disability, and early demise." (PMID 33204590, 2020). "The clinical presentation of ACAD9 deficiency is dominated by cardiomyopathy." (PMID 30025539, 2018). "We found that cardiomyopathy was more prevalent in patients with ACAD9 and NDFUA11 mutations." (PMID 22644603, 2012). "Mutations in ACAD9 have been associated with conditions such as cardiomyopathy, muscular weakness, and exercise intolerance, and in rare cases, patients may also present with other symptoms, such as epilepsy, intellectual deficits, and severe developmental delays." (PMID 39273702, 2024). "Mitochondrial acyl-CoA dehydrogenase family member 9 (ACAD9) is essential for the assembly of mitochondrial respiratory chain complex I. Disease causing biallelic variants in ACAD9 have been reported in individuals presenting with lactic acidosis and cardiomyopathy." (PMID 30025539, 2018). "ACAD9 levels are altered in mitochondria-related diseases, including mitochondrial encephalomyopathy and cardiomyopathy." (PMID 37529234, 2023). "Although both ACAD9 and VLCAD deficiency can present with cardiomyopathy, the clinical phenotype is otherwise distinct, with hypoglycemia, rhabdomyolysis and liver failure, typically seen in VLCAD." (PMID 30025539, 2018). "However, mutations in another factor, ACAD9, which also associates with NDUFAF1 and ECSIT, appear to be a relatively common cause of complex I deficiency presenting as cardiomyopathy and/or exercise intolerance." (PMID 34032637, 2021). "Nonetheless, ACAD9 mutation seems to show a different pathology from the one observed in LS; ACAD9 mutations are associated with a non-Leigh complex encephalopathy and often cardiomyopathy in most cases." (PMID 40149709, 2025).
lactic acidosis (6 papers, 2016 to 2025). Metabolic acidosis characterized by the accumulation of lactate in the body. "The clinical presentation in ACAD9 deficiency includes lactic acidosis, neurological symptoms with development delay and a low IQ, hepatic disorders, cardiac diseases and myopathy which causes muscular weakness and easy fatigability." (PMID 41425985, 2025). "Genetically deficit in ACAD9 commonly linked to cardiac symptoms, neurological symptoms, and severe lactic acidosis." (PMID 36482121, 2023). "One infant with severe lactic acidosis was found to carry two heterozygous variants in ACAD9, which was associated with isolated complex I deficiency and diffuse hypergranular hepatocytes." (PMID 27483465, 2016). "941T>C and c.187G>T, mutations in ACAD9 may present with lactic acidosis and severe coagulopathy phenocopying severe MDS highlights the importance to consider NGS early in the diagnostic evaluation of infants with ALF." (PMID 27483465, 2016).
hypertrophic cardiomyopathy (3 papers, 2020 to 2025). A condition in which the myocardium is hypertrophied without an obvious cause. "Two patients harbored variants in ACAD9 and presented a hypertrophic cardiomyopathy (HCM) phenotype." (PMID 37240454, 2023). "We present a patient with mitochondrial myopathy, hypertrophic cardiomyopathy, and epilepsy due to recessive ACAD9 mutations." (PMID 33204590, 2020). "A patient with a mild and late-onset phenotype, suffering from exercise intolerance and hypertrophic cardiomyopathy, was diagnosed as a compound heterozygote of the ACAD9 gene." (PMID 40806260, 2025).
liver dysfunction (3 papers, 2010 to 2025). "ACAD9 deficiency in humans can lead to acute liver dysfunction and hypoglycemia, and deletion of medium chain acyl-CoA dehydrogenase (Acadm), immediately downstream of Acad9 in the mitochondrial long-chain β-oxidation pathway, profoundly affects hepatic glucose metabolism." (PMID 20668691, 2010).
breast carcinoma (2 papers, 2016 to 2021). "To the best of our knowledge, we could not find experimental data which linked ACAD-9 to breast cancer." (PMID 27112211, 2016). "For the first time, in this study, we identified an ACAD9 variant (Ala326Thr) that was detected in every affected individual with PDAC or its precursor lesions in 4 of 46 (8.7%) FPC families that were characterized by the absence of breast cancer in the pedigree." (PMID 34357098, 2021). "As none of these families reported breast cancer in the pedigree, affected members of an additional 31 FPC families without breast cancer were Sanger sequenced to determine the status of the ACAD9 gene." (PMID 34357098, 2021).
cardiac hypertrophy (2 papers, 2025). "ACAD9 variants are the most frequent cause of cardiac hypertrophy and isolated complex I deficiency in childhood." (PMID 41425985, 2025). "In the presence of any, even mild, paediatric cardiac manifestation, and in case of early onset cardiac hypertrophy combined with elevated serum lactate levels, ACAD9 mutation should be investigated." (PMID 41425985, 2025). "ACAD9 deficiency is usually associated with cardiac hypertrophy." (PMID 40806260, 2025).
glycogen storage diseases (2 papers, 2019 to 2025). "Mitochondrial disorders, such as ACAD9 deficiency, and glycogen storage diseases [e.g., debrancher enzyme or phosphorylase kinase B deficiency] may also manifest with hypertrophy and systemic signs." (PMID 40868441, 2025).
heart failure (2 papers, 2016 to 2023). Inability of the heart to pump blood at an adequate rate to meet tissue metabolic requirements. "A homozygous variant in ACAD9 was identified in the proband of a Swedish family where family members reported stroke with intracerebral bleeding and progressive muscle and heart failure." (PMID 36973604, 2023). "Variants in ACAD9, encoding the mitochondrial enzyme acyl-CoA 9 dehydrogenase, were detected in subject #12, who developed liver and heart failure soon after birth." (PMID 27483465, 2016).
Stroke (2 papers, 2023 to 2025). Sudden impairment of blood flow to a part of the brain due to occlusion or rupture of an artery to the brain. "On the other hand, one homozygous variant, ACAD9 c.976G>A (p.Ala326Pro), was identified in the proband (stroke before 56 yo) of a family where two family members had developed stroke." (PMID 40650005, 2025). "Among these, three are likely monogenic causes of stroke (ELN, SCN5A, and VHL genes), two are considered risk factors (FV and ADAMTS13), two have conflicting interpretations (ACAD9 and ENG), and three are most likely benign (CBS, PMM2, and PKD1)." (PMID 40650005, 2025).
cardiac arrest (1 paper, 2023). Cessation of breathing and/or cardiac function. "After a sudden cardiac arrest, muscle biopsy was re-analyzed, and the characterization of muscle cDNA showed the presence of a second ACAD9 variant, classified as VUS." (PMID 37240454, 2023).
colon cancer (1 paper, 2019). "Data from TCGA database analyses also revealed that approximately 50% of colon cancer patients had elevated ACAD9 mRNA levels, while the majority of patients displayed a reduction in ACADS mRNA." (PMID 31623618, 2019). "The expression of MYC, LEF1, PPARδ, and ACAD9 were closely correlated in a Western blot comparing colon cancer and normal adjacent benign tissue of human samples." (PMID 31623618, 2019). "LEF1 was also necessary for maximum expression of PPARδ and ACAD9 in the fully transformed DLD1 colon cancer cells." (PMID 31623618, 2019).
esophageal cancer (1 paper, 2021). A primary or metastatic malignant neoplasm involving the esophagus. "However, recent publications suggest possible roles for ACAD9 in several cancers, such as prostate and esophageal cancer." (PMID 34357098, 2021).
glioma (1 paper, 2022). A benign or malignant brain and spinal cord tumor that arises from glial cells (astrocytes, oligodendrocytes, ependymal cells). "IHC analysis revealed that the three essential FAO enzymes CPT1A, CPT2, and ACAD9 were increased 86.96, 84.78, and 76.09% respectively in the recurrent gliomas, companied with 82.6% CD47 enhancement." (PMID 35314680, 2022).
lymphoma (1 paper, 2023). A malignant (clonal) proliferation of B- lymphocytes or T- lymphocytes which involves the lymph nodes, bone marrow and/or extranodal sites. "We further hypothesize that lymphoma susceptibility might be aggravated by the additional mutations in FBP1 and ACAD9, affecting energy metabolism and – potentially – killing activity in NK cells and CTLs." (PMID 37388727, 2023).
mitochondrial cytopathies (1 paper, 2025). "The analysis of a panel of 368 nuclear genes involved in mitochondrial cytopathies highlighted two variants in the ACAD9 gene: a c.1240C> T p.Arg414Cys class 5 variant, which is already described, and a c.1636G> A p.Val546Met class 3 or 4 variant, which has never been identified or reported." (PMID 40806260, 2025).
Myalgia (1 paper, 2025). "Second, APC, ENO3, ACAD9, RNASEH1, FKTN, DYSF, and ATP2A1 are associated with Myalgia." (PMID 40831500, 2025).
osteoporosis (1 paper, 2026). A condition of reduced bone mass, with decreased cortical thickness and a decrease in the number and size of the trabeculae of cancellous bone (but normal chemical composition), resulting in increased fracture incidence. "Here, we identify ACAD9 deficiency as a clinically relevant risk factor for fragility fractures and reveal a previously unrecognized cytosolic function of ACAD9 in suppressing osteoclast differentiation, thereby protecting against osteoporosis." (PMID 41888097, 2026).
ovarian carcinoma (1 paper, 2007). A malignant neoplasm originating from the surface ovarian epithelium. "In one of these genes, namely ACAD9, we experimentally observed exonization in two ovarian cancer cell lines, but not in mRNA extracted from seven nonovarian cell lines." (PMID 17594509, 2007).
pancreatic disease (1 paper, 2021). "In all four families, the ACAD9 variant co-segregated with the pancreatic disease." (PMID 34357098, 2021). "The present WGS, however, detected potentially pathogenic variants in the ATM, SUFU, DAB1, POLQ, MAP3K3, FGFBP3 and ACAD9 genes that co-segregated with pancreatic disease in single FPC families, and thus might predispose them to the disease." (PMID 34357098, 2021). "A new finding of the present study is that affected patients from one FPC family can carry identical germline variants in up to three different genes, e.g., DAB1, POLQ and FGFBP3 in family 25-9-44 or MAPK3 and ACAD9 in family 25-4-46, which segregate with pancreatic disease." (PMID 34357098, 2021).
mitochondrial disease (5 papers, 2019 to 2025). "However, some mitochondrial disease aetiologies exhibit a combination of defects in both OXPHOS and FAO, including Long-chain 3-hydroxyacyl-CoA dehydrogenase (LCHAD), Medium-chain acyl-CoA dehydrogenase (MCAD) and acyl-CoA dehydrogenase family member 9 (ACAD9) deficiencies." (PMID 36293464, 2022). "Since the detection of the first mitochondrial disease gene ACAD9 by NGS in 2010, the number of reported mitochondrial disease genes has duplicated, exemplifying the technology’s diagnostic power." (PMID 33324649, 2020).
myopathy (4 papers, 2020 to 2025). A disease of the muscle in which the muscle fibers do not function properly. "A heterozygous ACAD9 variant was assumed to underlie the mildly increased creatine kinase levels and myopathy of brothers V and VII, but no genetic analysis could be performed." (PMID 37388727, 2023).
tumor (3 papers, 2020 to 2022). "A mutation analysis of the ACAD9 gene confirmed the same variant in the tumor tissue as that detected in the blood DNA." (PMID 34357098, 2021). "Indeed, ET treatment or in CPT1A−/−, CPT2−/−, and ACAD9−/− cells, radiation-mediated elimination of the clonogenic tumor cells by 25–50%." (PMID 35314680, 2022).
cancer (2 papers, 2021 to 2025). A tumor composed of atypical neoplastic, often pleomorphic cells that invade other tissues. "Additionally, ACOX3, ACAD9, ACAD10, ACOT1, ACOT8, and DECR2 displayed positive associations with PEBP1/STK11 co-expression across various cancer types, highlighting a potential involvement in enhancing fatty acid metabolism in the context of PEBP1/STK11 expression." (PMID 40806276, 2025).
ACAD9 also shares sentences with these, for which no sentence is quoted: cardiac diseases (2 papers); epilepsy (2); Hypoglycemia (2); Leigh disease (2); Mitochondrial myopathy (2); mitochondrial oxidative phosphorylation disorder (2); Alstrom syndrome (1); bleeding (1); carnitine deficiency (1); colorectal cancer (1); Desminopathy (1); developmental delays (1); familial dilated cardiomyopathy (1); genetic diseases (1); Griscelli syndrome type 2 (1); hepatic disorders (1); hereditary hemorrhagic telangiectasia (1); hypopharyngeal cancer (1); ichthyosiform erythroderma (1); Immunodeficiency (1); Insulin resistance (1); Intellectual disability (1); ischemia (1); lipid storage myopathy (1); liver failure (1); long QT syndrome (1); Marfan syndrome (1); Metabolic disorders (1); mitochondrial encephalomyopathy (1); movement disorder (1).
A further 8 diseases each share a sentence with ACAD9 in 1 paper.